TANK (TRAF family member associated NFKB activator)
Diseases named in the same sentence as TANK in open-access papers:
TANK is named in the same sentence as 26 diseases in open-access papers, as found by Europe PMC text mining. Sharing a sentence is not in itself a finding about the gene and the disease. The quoted sentences say what the papers report.
breast carcinoma (5 papers, 2013 to 2025). "Two SNPs (rs17705608 and rs7309) in the TANK gene have been associated with breast cancer risk, involving TNF-mediated signal transduction." (PMID 37226243, 2023). "TNFSF10, -13 and -13B were upregulated whereas TNFSF2, -12, -14, and TANK were unaffected in breast cancer compared to normal adjacent breast tissue." (PMID 35432372, 2022). "Among this short list, GADD45A, TANK and TACC2 are already known risk related factor in breast cancer." (PMID 28621677, 2017). "Although this study suggested variation in four genes, MAP3K1, MMP9, TANK, and TLR9, may affect the risk of breast cancer, previous studies have observed associations for other genes in TLR or NFκB pathways." (PMID 23634849, 2013). "Totally 15 breast cancer risks genes were obtained (Benjamini & Hochberg FDR < 0.05) and 6 of them (FAM84B, AAGAB, RPS25, SH3BP4, KRT80, TANK) showed the most significant correlation with the patient survival." (PMID 28621677, 2017).
virus infection (4 papers, 2010 to 2022). "Using a microarray-derived gene expression signature of TBK1 in response virus infection or poly(I∶C) stimulation, we found that TBK1 activation was strictly dependent on the integrity of the TBK1/TANK interaction." (PMID 21931631, 2011). "TRAF3 is a critical signalling molecule for IFNβ activation in response to virus infection, and is a well established binding partner for the TBK1 adaptor protein TANK, residing in a trimeric complex containing TBK1." (PMID 20174559, 2010). "The results indicate that TANK is potent to suppress induction of type I IFNs in response to DNA, but not RNA, virus infection." (PMID 34819357, 2022).
cervical cancer (2 papers, 2023). A primary or metastatic malignant neoplasm involving the cervix. "TANK has also been reported to be aberrantly expressed in cervical cancer and is associated with apoptosis in osteosarcoma." (PMID 38062023, 2023).
COVID-19 (2 papers, 2022 to 2023). A disease caused by infection with severe acute respiratory syndrome coronavirus 2. "The results revealed various diseases from the common DEGs of AKI, CKD, and COVID-19, which include DUSP6, NRIP1, TNFAIP8, S1PR1, and TANK." (PMID 37026010, 2023). "Upregulated genes in early COVID-19 mortality included many involved with interferon signaling (e.g., GBP2, ISG15), the NF-κB pathway (e.g., NFKB2, NFKBIA), and TNF-α and IL-1 signaling (e.g., TANK, NOD1, RELA)." (PMID 35446789, 2022).
glioblastoma (2 papers, 2013 to 2023). The most malignant astrocytic tumor (WHO grade IV). "Although increased expression or dysregulation of both kinases has been described for a variety of human cancers, this study shows that deregulated expression of the TANK protein is frequently occurring in glioblastomas (GBMs)." (PMID 24217713, 2013). "Deregulated expression of TANK not only orchestrates the signaling network of the ERK1/2, AKT and IRF3 pathways in controlling the survival, proliferation, migration and invasion of glioblastoma (GBM) cells but also mediates the relative expression of genes in inflammatory signaling cascades." (PMID 37215097, 2023).
glioma (2 papers, 2013 to 2023). A benign or malignant brain and spinal cord tumor that arises from glial cells (astrocytes, oligodendrocytes, ependymal cells). "High expression of TANK is associated with the malignant phenotype of glioma, as it shapes an immunosuppressive tumor microenvironment." (PMID 37215097, 2023). "In addition, the qPCR and IHC results indicated that higher TANK expression was associated with more malignant phenotypes in glioma (P < 0.05)." (PMID 37215097, 2023). "Thus, higher TANK expression is associated with more malignant glioma phenotypes." (PMID 37215097, 2023). "Then, we systematically evaluated the relationship between TANK expression and immune characteristics in the glioma microenvironment." (PMID 37215097, 2023). "TANK expression was higher in gliomas with wild-type IDH than in those with mutant IDH in the three cohorts (P < 0.05)." (PMID 37215097, 2023). "We found that immunosuppressive oncogenic pathways were significantly enriched in gliomas with high expression of TANK (P < 0.05)." (PMID 37215097, 2023). "TANK was specifically overexpressed in glioma and enriched in the malignant phenotype, and its overexpression was related to poor prognosis." (PMID 37215097, 2023). "Immunohistochemical analysis of the tissue microarrays revealed that TANK was upregulated in gliomas (P < 0.05)." (PMID 37215097, 2023). "The possibility that TANK is a potential immunotherapeutic target for glioma needs further exploration." (PMID 37215097, 2023). "TANK was significantly enriched in glioma with WHO grade IV, wild-type IDH1, and GBM (P < 0.05) (P < 0.05)." (PMID 37215097, 2023). "In conclusion, high expression of TANK indicates a malignant phenotype of glioma, predicts a poor prognosis and shapes an immunosuppressive tumor microenvironment." (PMID 37215097, 2023). "In the TCGA cohort, higher grade glioma tissues expressed significantly higher levels of TANK than lower grade glioma tissues (P < 0.001)." (PMID 37215097, 2023). "Correlation analysis between TANK expression and infiltration of protumor immune cells in the TCGA cohort revealed that gliomas with high TANK expression contained more immunosuppressive cells, except for CD56dim NK cells (P < 0.05)." (PMID 37215097, 2023). "In two in-house cohorts, glioma patients with high expression of TANK generally had shorter OS and PFS times than those with low expression of TANK, as determined by qPCR and IHC (log-rank test P < 0.05)." (PMID 37215097, 2023). "In four cohorts, the immune and stromal scores were higher in gliomas with high TANK expression than in gliomas with low TANK expression (P < 0.05)." (PMID 37215097, 2023). "In this study, TANK was highly expressed in glioma (P < 0.05), as confirmed by qPCR and IHC (P < 0.05)." (PMID 37215097, 2023). "Gliomas with high TANK levels exhibited enrichment in immunomodulatory pathways, including “hypoxia”, “angiogenesis”, “inflammatory response”, “NF-kappaB signaling”, and “IL6/STAT3 signaling” in the TCGA cohort." (PMID 37215097, 2023). "Third, more functional experiments are needed to validate the role of TANK in the glioma microenvironment, especially the immune microenvironment." (PMID 37215097, 2023). "In addition, the levels of CXCL9, CXCL10, and CCR3, which increase the recruitment of CD8+ T cells into the microenvironment of glioma, were increased in gliomas with high TANK expression." (PMID 37215097, 2023). "Similarly, for gliomas with high expression of TANK, one of the previous treatment methods was to transform the immunosuppressive microenvironment into an immune-activated state, thus triggering the anticancer immune response." (PMID 37215097, 2023). "Considering that TANK expression is correlated with glioma malignancy, we inferred that abnormal expression of TANK might promote the progression of glioma." (PMID 37215097, 2023). "In the in-house cohort, TANK expression was high in glioma tissues (P < 0.001)." (PMID 37215097, 2023).
glioma (continued). "Although TRAF-associated NF-kB activator (TANK) interacts and cross-regulates with cytokines and microenvironmental immune cells, it is unclear whether TANK plays a role in the immunologically heterogeneous gliomas." (PMID 37215097, 2023). "Importantly, the abundances of most immunosuppressive cells were higher in gliomas with high TANK expression in the four cohorts (P < 0.05)." (PMID 37215097, 2023). "Given that TANK may remodel the tumor microenvironment through immunobiological processes, the distribution of 35 immune cell types in gliomas with high and low expression of TANK was examined in the TCGA cohort." (PMID 37215097, 2023). "Our results are consistent with previous results, indicating that TANK could play a protumorigenic role in glioma, and consistent with previous results." (PMID 37215097, 2023). "Furthermore, we found that gliomas with high levels of TANK consistently exhibited higher immune and stromal scores than those with low levels of TANK in four cohorts (P < 0.05), indicating that TANK may regulate immune and stromal cells." (PMID 37215097, 2023). "Therefore, we inferred that TANK shapes an inflamed TME in glioma." (PMID 37215097, 2023). "Furthermore, TANK was identified as a marker of poor prognosis in glioma." (PMID 37215097, 2023). "Additionally, we evaluated the ability of TANK to predict treatment response in glioma." (PMID 37215097, 2023). "Additionally, we examined the expression pattern of TANK in four cohorts of patients with glioma." (PMID 37215097, 2023). "Although the role of TANK in regulating the tumor microenvironment of glioma has not been reported in previous studies, its important role in other tumors has been reported." (PMID 37215097, 2023). "Moreover, TANK indirectly phosphorylates the transcription factor STAT3 to increase the release of interleukin-6 (IL-6) and ultimately accelerate the progression of glioma in terms of enhanced angiogenesis and proliferation." (PMID 37215097, 2023). "However, the clinical significance and expression pattern of TANK in glioma have not been reported." (PMID 37215097, 2023).
atherosclerosis (1 paper, 2007). A disease characterized by the build-up of fatty material and calcium deposition in the arterial wall resulting in partial or complete occlusion of the arterial lumen. "Similarly to what observed with anti-US28 peptide antibodies, anti-UL122 antibodies induced up-regulation of transcription factors, in particular genes involved in NF-kB activation pathway such as TANK and RELB, which have been implicated in atherosclerosis." (PMID 17534423, 2007).
autoimmune disease (1 paper, 2022). A disorder resulting from loss of function or tissue destruction of an organ or multiple organs, arising from humoral or cellular immune responses of the individual to their own tissue constituents. "To determine the involvement of TANK in the development of DAH, we took advantage of pristane, which induces SLE-like autoimmune disease including DAH in mice depending on type I IFN signaling." (PMID 34819357, 2022).
Autoimmunity (1 paper, 2022). The occurrence of an immune reaction against the organism's own cells or tissues. "Therefore, the cGAS-STING pathway might be suppressed by TANK even in human SLE patients to prevent pathogenesis of autoimmunity and the development of DAH." (PMID 34819357, 2022). "Given that the NF-kB signaling pathway is also negatively regulated by TANK, enhanced activation of proinflammatory cytokines by NF-kB, but not type I IFNs, via the lack of TANK can be more important for the development of long-term autoimmunity." (PMID 34819357, 2022).
blood disease (1 paper, 2023). A disease that occurs in the blood. "RBMS1 is associated with DNA binding and is associated with the blood disease ‘blue toe syndrome’, while TANK is associated with signal transduction and the TRAF pathway and is associated with infectious neurological disorders (Nipah virus encephalitis)." (PMID 36672117, 2023).
lupus (1 paper, 2022). "In this study, we investigated the role of TANK in a pristane (2.3.-tetramethylpentadecan, TMPD)-induced lupus model, and found that TANK is essential for the prevention of fatal DAH by inhibiting lung vascular endothelial cell death." (PMID 34819357, 2022). "Collectively, TANK inhibits the cGAS-dependent recognition of cytoplasmic DNA to prevent fatal DAH in the murine lupus model." (PMID 34819357, 2022). "Here, we show that TANK, a negative regulator of the NF-κB signaling via suppression of TRAF6 ubiquitination, is critical for the amelioration of fatal DAH caused by lung vascular endothelial cell death in a mouse model of systemic lupus erythematosus." (PMID 34819357, 2022).
lupus nephritis (1 paper, 2016). Glomerulonephritis in the context of systemic lupus erythematosus. "The lupus nephritis that develops in TANK-KO mice, and which is driven by hyperactivation of the MyD88 signaling network, was similarly prevented by crossing to IL-6–KO mice." (PMID 27807192, 2016).
malignant glioma (1 paper, 2023). A grade III or grade IV glioma arising from the central nervous system. "Meanwhile, TANK and TBK1 can stabilize each other in malignant glioma, with TBK1 being crucial to TANK’s function." (PMID 38062023, 2023).
oral cancer (1 paper, 2023). "This study permitted the proposal of 8 salivary biomarkers for oral cancer in patients previously infected with HPV (RPRD2, PSCA, MCM2, CDKN2A, BAK1, HSPA1A, TANK, MAP2K1)." (PMID 37599356, 2023).
type II diabetes (1 paper, 2025). "A study analyzing gene expression between individuals with type II diabetes and controls found differential expression of the RIG‐I‐like receptor signaling pathway, highlighting the genes TBK1, ATG5, TANK, IL8, and MAVS." (PMID 40476695, 2025).
infection (9 papers, 2009 to 2025). The state of being infected such as from the introduction of a foreign agent such as serum, vaccine, antigenic substance or organism. "Subsequently, TANK deficient cells were shown to display normal responses to infection with RNA viruses." (PMID 23028469, 2012). "In addition, the expression of SARM gene was 1.5 folds increased while the activation of TANK gene was undetectable during ADE-infection." (PMID 21200427, 2010). "Strikingly, TANK phosphorylation upon EHEC and ΔEhaF infection was greatly reduced in Tfe3−/− cells indicating that TFE3 is essential for TANK phosphorylation." (PMID 37041208, 2023). "The expression of MDA5, TANK and P-IRF3 protein decreased significantly (P < 0.01) after HEK-293 T cells infection with EMCV while the expression of MAVS and IRF3 protein showed no significant change." (PMID 34587973, 2021). "Expression levels of SARM and TANK were significantly increased at 3 hr post DENV-ADE infection, but not in DENV infection." (PMID 21200427, 2010). "Thus we investigated whether or not down-regulation of the TLR-dependent signaling pathway is due to DENV-ADE infection activating negative regulators of TLRs signaling such as SARM and TANK and so the levels of SARM and TANK gene expression were investigated." (PMID 21200427, 2010).
tumor (8 papers, 2013 to 2025). "Second, the role of TANK in the tumor microenvironment and its underlying regulatory mechanisms need to be further explored." (PMID 37215097, 2023). "We examined TANK expression in 29 normal tissues and 200 fresh tumor tissues, as well as in 27 paired tumor samples and peritumor tissues by qPCR." (PMID 37215097, 2023). "Analysis of the TCGA cohort showed higher TANK expression in tumor tissues than in normal brain tissues, and analyses of the GSE16011 and Rembrandt cohorts validated this observation (P < 0.001)." (PMID 37215097, 2023). "Previous studies have shown that downregulation of TANK can arrest cells in S-phase and prevent tumor cell migration." (PMID 37215097, 2023). "TANK levels in various tumor tissues, including LGG and GBM tissues, were markedly higher than those in nontumor tissues (P < 0.05)." (PMID 37215097, 2023). "Orthotopic xenografts model in NOD-SCID IL2Rγ null mice and stereotactic injection of HER2.taNK in tumor area have displayed inhibition of the tumor progression." (PMID 30567306, 2018). "Specifically, decreased expression of TANK and ENPP1—both associated with immune evasion and tumor progression—suggests that SKD may attenuate immunosuppressive pathways in these cells." (PMID 41301480, 2025). "Furthermore, TANK was significantly overexpressed in tumor tissues in 35 tumor-peritumor tissue pairs (P < 0.001)." (PMID 37215097, 2023). "Furthermore, the tumor tissues exhibited significantly higher levels of TANK expression than the matched peritumor tissues (P < 0.001)." (PMID 37215097, 2023). "In summary, TANK plays a vital role in the tumor microenvironment." (PMID 37215097, 2023). "Therefore, we hypothesized that TANK might be involved in the remodeling of the tumor microenvironment." (PMID 37215097, 2023). "The functional relevance of TANK was analyzed in a panel of GBM-derived cell lines and revealed that knockdown of TANK arrests cells in the S-phase and prohibits tumor cell migration." (PMID 24217713, 2013). "Subsequently, we performed quantitative reverse-transcription polymerase chain reaction (qRT-PCR) to examine the expression levels of the seven key prognostic genes—CEBPB, TANK, MAT2B, TMEM165, CCDC167, CYFIP1, and COX17—in the CEBPB+CAF prognostic model in the tumor tissues." (PMID 40145099, 2025). "As the excised GBM material contains heterogeneous cell populations and also some nontransformed cells surrounding the tumor, it was then interesting to compare TANK expression levels in GBM cell lines." (PMID 24217713, 2013).
cancer (6 papers, 2013 to 2025). A tumor composed of atypical neoplastic, often pleomorphic cells that invade other tissues. "Those genes contributing to ‘defense response’ and ‘peptidase activity’ terms in recurrent tissues were mainly composed of a number of genes previously associated with cancer such as S100A8, S100A9, TANK, or ADORA2B." (PMID 37177979, 2023). "Moreover, TANK expression was positively correlated with PD-L1, PD-1, and CD44 expression in various cancers." (PMID 37215097, 2023). "Another NFκB gene we investigated was TANK (also known as TRAF2), which is a critical upstream component in the NFκB activation pathway and therefore could be a factor that relates to inflammation as well as cancer development and progression." (PMID 23634849, 2013). "Besides, the roles of seven genes (NR1D2, TANK, LRSAM1, PLXNA1, INHBE, HDGF, and ARAF) in SCLC have not been reported, however those genes have been reported to play a vital role in other type cancer." (PMID 34741430, 2021).
TANK also shares sentences with these, for which no sentence is quoted: anaplastic astrocytoma (1 paper); anaplastic large cell lymphoma (1); anemia (1); Ascites (1); Burkitt lymphoma (1); hairy cell leukemia (1); HTLV infection (1); osteosarcoma (1).